ZEB2 (zinc finger E-box binding homeobox 2)
Diseases named in the same sentence as ZEB2 in open-access papers (continued):
Sharing a sentence is not in itself a finding about the gene and the disease.
cancer (continued). "Although studying the functional role of EMT proteins is not within the scope of this study, previous studies demonstrated that TWIST1 and ZEB2 have other roles including repressing cellular senescence and conferring stem-like properties to cancer cells respectively." (PMID 26214683, 2015). "In addition, up-regulation of many factors (zeb2, kras, slug and snail) has also been reported in many cancers, which were well known to inhibit E-cadherin expression via different pathway." (PMID 25871475, 2015). "In particular, HuR regulates the expression of several genes implicated in establishing cancer traits and in silico predictions from RBPDB database showed several possible interaction sites through the 3′UTR region of ZEB2 mRNA, mostly at the beginning of the 3′UTR." (PMID 26136338, 2015). "As ZEB2 is associated with cancer stem cell properties and EMT, honokiol could inhibit metastasis as well as the stem-like properties of cancer cells at least partly through the miR-141/ZEB2 pathway." (PMID 26305257, 2015). "In cancers of liver and pancreas, ZEB2 is epigenetically silenced." (PMID 25798919, 2015). "The important role of transcription factor ZEB2 has been strongly underlined in numerous papers, due to its function in inducing epithelial- mesenchymal transition (EMT) and facilitating the metastasis of cancer cells." (PMID 24626466, 2014). "In the glioblastoma cell lines, it has been demonstrated that high ZEB2 levels could suppress E-cadherin, thereby regulating cancer cell differentiation." (PMID 25197668, 2014). "High levels of Zeb1 and/or Zeb2 in various cancers accompany bad prognosis." (PMID 23531534, 2013). "Indeed, silencing ZEB2 induced cancer cell apoptosis and reduced their viability." (PMID 41228271, 2025). "Future work can incorporate other critical genes or circuits (and/or other hallmarks of cancer), e.g., important EMT factors TWIST, SNAIL2 and ZEB2, into the models of cancer regulatory networks, which may provide more insights into underlying regulatory mechanisms for cancer metastasis and CAC." (PMID 39258786, 2024). "Moreover, the delivery of miR-192-5p inhibited the cytotoxic activity of CTLs and contributed to cancer immune escape by downregulating zinc finger E-box binding homeobox 2 (ZEB2), a transcription factor that modulated the expression of terminal effector genes in CD8+ T cells." (PMID 37767098, 2023). "Thus, we investigated whether there was a correlation between ZEB2 and the infiltrating immune cells in various cancers, including OV." (PMID 35723302, 2022). "Interestingly, our findings reveal that ZEB2 has a positive correlation in all cancers." (PMID 35723302, 2022). "However, the correlation between ZEB1 and ZEB2 in cancer is yet to be elucidated." (PMID 35723302, 2022). "In addition, it was confirmed that the mRNA level of ZEB2 was different in various cancers." (PMID 35723302, 2022). "Interestingly, we also observed that cancer patients with this expression pattern have poor prognosis, indicating that the miR-192-5p/ZEB2 axis could be relevant in the immune evasion of tumors during cancer progression." (PMID 33066331, 2020). "Furthermore, SNHG12 may serve as a promotor in multiple cancer-related pathways, such as Slug/zinc finger E-box-binding homeobox 2 (ZEB2) pathway, Notch2/Notch pathway, phosphatidylinositol 3-kinase (PI3K)/AKT pathway, and Wnt/β‐catenin signaling pathway." (PMID 33124951, 2020). "During EMT, cancer cells lose their cell-to-cell attachment by decreasing E-cadherin expression, due to hypermethylation of the promoter region or transcriptional repression caused by Zinc finger E-box-binding homeobox 1 (ZEB1), ZEB2, Snail, Slug (also known as SNAI2), and TWIST." (PMID 29758011, 2018). "Our study demonstrates that ZEB2 induces survival and subsequent seeding of CTCs, maybe through direct upregulation of pro-survival factors such as survivin and bcl-2, and thus probably contributes to cancer cell dissemination in vivo." (PMID 29416649, 2018).
cancer (continued). "Furthermore, a highly significant reverse correlation between RAB25 and ZEB2 expression in several human cancer types could be identified." (PMID 30445998, 2018). "Hence, ZEB2 is specifically required for invasive capacity during cancer metastasis." (PMID 29963231, 2018). "Moreover, an inverse correlation between miR-30a-5p and ZEB2 expression levels was discovered in ccRCC tissues obtained from both the First Affiliated Hospital and Cancer Center of Sun Yat-sen University (r=−0.33, P<0.001) and the TCGA database (r=−0.18, P<0.0001)." (PMID 28569782, 2017). "Thus, apart from its general role as an EMT inducer, ZEB1 and ZEB2 may have multiple functions that will be elucidated by analyses in specific cancer types in the future." (PMID 28618162, 2017). "Thus, we postulated the atypical E3 ubiquitin ligase SPFFbxo45 complex might also make contributions to EMT processes by mediating the ubiquitin-dependent degradation of EMT-TFs, particularly Zeb1 and Zeb2 proteins in cancer cells." (PMID 25460509, 2015). "Moreover, ZEB2 might be a new target for anticancer therapy because it plays a critical role in cancer cells." (PMID 23658743, 2013). "Given the critical role of Akt, ZEB1, and ZEB2 in cancer progression, the findings from this study provide additional novel evidence that Akt activation may play an important role in arsenic lung carcinogenesis by promoting As-transformed HBEC migration and invasion." (PMID 21954225, 2012). "The epithelial-mesenchymal transition (EMT) drives cancer progression, regulated by transcription factors (TFs) such as SNAI1, SNAI2, ZEB1, ZEB2, and TWIST." (PMID 41481650, 2026). "It is known to target key transcription factors such as ZEB1 and ZEB2, which are pivotal in promoting EMT and enhancing the invasive potential of cancer cells." (PMID 39859424, 2025). "For example, miR-200 is emerging as a novel star miRNA by targeting the transcription factors ZEB1 and ZEB2 to inhibit EMT and thereby prevent further development of malignant tumors." (PMID 40004224, 2025). "ZEB1 (zinc finger E-box binding Hox 1) and ZEB2 functioned as transcription factors, stimulating invasion and migration by enhancing EMT in cancer cells." (PMID 40075616, 2025). "CDH2, ZEB2, SNAI2, and SNAI1 are important regulatory genes that increase the motility and invasion capacity of cancer cells." (PMID 41179704, 2025). "The expression of ZEB2, a downstream target of miR-192 and a driver of EMT, regulates EMT and invasion in cancers." (PMID 40087755, 2025). "First, we noted that CDS1-high cancer cells express high levels of the epithelial marker gene E-cadherin (CDH1), whereas CDS1-low cancer cell lines express mesenchymal markers like ZEB1, ZEB2 and vimentin (VIM) 48,49." (PMID 40615674, 2025). "Due to their central role in EMT and extensive studies in cancer, ZEB1, ZEB2, SNAI1, SNAI2 and TWIST1 are considered as the core EMT-TFs." (PMID 39164745, 2024). "The melatonin treatment reduced the expression levels of ZEB1 and ZEB2 and some other EMT-relevant factors, thus decreasing the EMT and inhibiting the invasion properties of SKOV3-derived cancer stem cells." (PMID 38473317, 2024). "In contrast, ZEB1 and ZEB2 inhibit the expression of the miR-200 family, thus creating a feedback loop that promotes EMT and cancer cell aggressiveness." (PMID 39224263, 2024). "The induction of EMT leads to cancer metastasis via EMT transcription factors including Snail, Slug, Twist, Zeb1, and Zeb2." (PMID 38393059, 2024). "In vitro and in vivo experiments showed similar functions of ZEB1 and ZEB2, that is, both inhibited cell proliferation, likely by inducing CDK inhibitors, and both promoted anti‐cancer drug resistance and motile properties." (PMID 39362647, 2024). "These miRs play a crucial role in regulating the epithelial-mesenchymal transition in different types of cancer by repressing the transcription factors ZEB1 and ZEB2 in a bidirectional manner." (PMID 39001526, 2024).
cancer (continued). "We discovered the TFs that are sequentially and significantly upregulated as carcinoma cells progress through the EMT process and demonstrated that ZEB1 and ZEB2 play pivotal roles in initiating and sustaining the EMT phenotype." (PMID 39256881, 2024). "The findings revealed that normal tissues exhibited higher expression levels of SNAI1, ZEB2, and VIM compared to cancer tissues, and cirrhotic tissues showed higher expression levels than cancerous tissues as well." (PMID 37386390, 2023). "The EMT core regulators ZEB1, ZEB2, Snail, Slug and TWIST1 are up-regulated in claudin-low cancers independently of the status of ER expression." (PMID 37504297, 2023). "Meanwhile, the critical transcription factors, including TWIST1, TWIST2, ZEB1, ZEB2, SNAI1 and SNAI2, participate in the EMT process, leading to cancer cell migration and invasion." (PMID 37794509, 2023). "Whereas SNAI1 was equally expressed or slightly downregulated in the partial-EMT subgroups of basal-like cancers, ZEB1, ZEB2, and TWIST1 were more highly expressed in cluster 1 that is defined by the EMT-up genes." (PMID 38111531, 2023). "Together with YAP1 several EMT-TFs (ZEB1, ZEB2, TWIST2) are upregulated in cancer cells after contact with fibroblasts." (PMID 36936987, 2023). "ZEB2 is a transcriptional repressor which induces EMT by suppressing E-cadherin expression, thus contributing to the invasiveness of malignant tumors." (PMID 35406495, 2022). "It has been indicated that the miR-200 family determines the epithelial phenotype of cancer cells by targeting the E-cadherin repressors ZEB1 and ZEB2 proteins." (PMID 34923813, 2022). "By binding with the promoter of E-cadherin gene, zinc finger E-box binding homeobox 2 (ZEB2) suppresses E-cadherin transcription and induces the EMT of cancer cells, thus facilitating cancer progression." (PMID 36193069, 2022). "It has been known that the PI3K-Akt pathway facilitates the expression of EMT-related transcription factors Snail, Slug, ZEB1, and ZEB2, thereby promoting EMT and enhancing the motility of cancer cells." (PMID 36009568, 2022). "ZEB2, a key activator of epithelial-mesenchymal transition (EMT), has been found to promote EMT processes in various cancer metastases." (PMID 36514044, 2022). "In line with this, various functional studies showed that the down-regulation of miR-200 induced EMT, whereas its overexpression provoked mesenchymal-to-epithelial transition (MET) and inhibited cancer cell motility by repression of ZEB1 and ZEB2." (PMID 36011331, 2022). "The miR-141-3p was found to be down-regulated in HCC tissues and it is known to regulate E2F3 and ZEB2 genes, which are up-regulated in HCC cancer." (PMID 35629174, 2022). "Zeb2 is mainly known for its role in the development of the nervous system and its ability to stimulate epithelial-to-mesenchymal transition (EMT) in cancer." (PMID 33909875, 2022). "This study investigated the specific regulatory mechanism of ZEB2 in COAD, a common cancer with high rates of morbidity and mortality." (PMID 36072677, 2022). "We also checked expression of EMT markers, such as E-Cadherin, Krt12, Vimentin, Survivin, Slug, ZEB1 and ZEB2, in the TNBC cancer cells, and found that expression of ZEB1 was positively correlated with expression of SENP1." (PMID 35342335, 2022). "Since EMT has been shown to be comprehensively involved in GCB resistance in several cancer types, subsequent comparisons were carried out among major transcription factors of EMT (EMT-TFs), including Snail, Slug, Twist1 and ZEB2." (PMID 33922395, 2021). "ZEB2 emerges as a prognostic predictive biomarker for CMS2 CRC, as confirmed by the inverse correlation between relapse-free survival and ZEB2 expression, which could be also relevant to identify cancers endowed with E/M traits and associated with high aggressiveness." (PMID 34408135, 2021).
cancer (continued). "The miR-200 family inhibits EMT, cancer growth, invasion, and metastasis via the inhibition of ZEB1 and ZEB2 (transcriptional regulators of E-Cadherin)." (PMID 34830196, 2021). "Interactions between the miR-200 family of miRNAs and ZEB1/ZEB2, two transcription factors that regulate epithelial to mesenchymal transition (EMT), inhibited EMT and suppressed cancer metastasis)." (PMID 34055490, 2021). "ZEB2 is a zinc-finger homeodomain transcription factor protein belong to ZEB family, ZEB2 play an essential role in neuronal development, also participate in Epithelial-mesenchymal transition (EMT) of cancer cell, wound healing and neural development in adult." (PMID 34852714, 2021). "They affect the cancer’s aggressiveness and myofibroblast transdifferentiation via directly binding to EMT inducers ZEB1 and ZEB2." (PMID 34208375, 2021). "Transcription factors known to regulate EMT include ZEB1, ZEB2, SNAI1 (SNAIL), SNAI2 (SLUG), and TWIST1 and have been suggested to promote cancer progression, including metastasis." (PMID 34339740, 2021). "Zeb2-NAT’s ability to control a fundamental process as EMT has been shown to favor the maintenance and metastasis of some human cancers." (PMID 33142861, 2020). "Among the cancer driver genes that experienced epigenetic changes in at least five cancer types, we identified eight genes: CEP55, PIF1, RRM2, NCAPH, ZEB2, CIT, FLI1, and PCDH17." (PMID 31900418, 2020). "The transcription factors, SNAI1, SLUG, ZEB1, and ZEB2, that are involved in EMT, repress E-cadherin to promote the mesenchymal features of cancer cells." (PMID 32218208, 2020). "It has been demonstrated that ZEB2 interacts with the transcription factor Sp1 to activate the expression of mesenchymal genes and vimentin expression, leading to EMT in human cancer cells." (PMID 32149094, 2020). "ZEB2 can directly bind to conserved E2 boxes of the E-cadherin promoter to repress E-cadherin expression, accelerating EMT and invasion in malignant epithelial tumors." (PMID 32149094, 2020). "ZEB1, ZEB2, SNAI1, and SNAI2 were significantly and positively correlated with the ESTIMATE immune score in all five cancer types examined." (PMID 31780722, 2019). "ZEB1, ZEB2, SNAI1, SNAI2 and FOXC2 exhibited consistent positive correlations with the ESTIMATE stromal score in all five cancer types." (PMID 31780722, 2019). "qPCR analyses revealed that the mesenchymal markers (i.e. SNAI1, SNAI2, ZEB1, ZEB2, CDH2, vimentin and fibronectin) expression was decreased in cancer EVs-exposed BRCA1-KO fibroblasts, while the expression of CDH1 was increased." (PMID 31200749, 2019). "This included the EMT-inducing zinc-finger E-box-binding homeobox factor (ZEB2) and the STAT3 target MMP2, which enhances the degradation of extracellular matrix proteins and cancer cell invasion." (PMID 30645971, 2019). "ZEB2 is originally defined as a transcription factor and executes epithelial-to-mesenchymal transition (EMT) procedures in embryonic development and cancer." (PMID 30979827, 2019). "The present study demonstrates that ZEB2 induces expression of Sp1-regulated genes such as survivin, bcl-2, cyclin D1, and VEGF by cooperating with Sp1 to promote cancer cell survival and endothelial cell activation directly during metastasis." (PMID 29416649, 2018). "ZEB2 acts as a transcriptional repressor of E-cadherin and increases invasion, and high levels of BMI1 is correlated with EMT characteristics in cancer cells." (PMID 30463333, 2018). "Various transcription factors such as Twist, Snail, Slug, ZEB1 and ZEB2 are known to orchestrate EMT by activating the crosstalk of signaling networks that confer traits of self-renewal and invasiveness to cancer cells." (PMID 29515112, 2018). "Amongst all these potential target genes, only ZEB2 was demonstrated to promote cell invasion, migration, and EMT progress in human malignant tumors." (PMID 30352837, 2018).
cancer (continued). "In this study, we found that ZEB2 upregulated survivin, cyclin D1, and vascular endothelial growth factor (VEGF) through cooperation with Sp1 to promote cancer cell survival and proliferation and endothelial cell activation." (PMID 29416649, 2018). "ZEB2 expression increased in NSCLC and it can induce epithelial-mesenchymal transition (EMT) to facilitate the metastasis of cancer cells." (PMID 29484121, 2018). "In other cancer cells, many genes have been identified as miR-338-3p targets, including ADAM17, PREX2a, ZEB2, Sox4, SMO, MACC1, and IRS2." (PMID 29618948, 2018). "Growing evidence indicates that the miR-200 family is involved in cancer cell migration via the targeting of ZEB1 and ZEB2." (PMID 29738527, 2018). "The transcription factors of EMT, such as ZEB1, ZEB2, Snail1 and Snail2, control EMT phenotype, which triggers cancer cell invasion." (PMID 28145431, 2017). "Further, they conclude that the interaction between TFAP2A and ZEB2 promoter affects ZEB2 expression, hence modulating the EMT process itself and providing evidence for a role of TFAP2A in cancer progression." (PMID 28412966, 2017). "Two proteins comprising the ZEB family of zinc finger transcription factors, ZEB1 and ZEB2, execute EMT programs in embryonic development and cancer." (PMID 28783176, 2017). "Some of the target genes were closely related to cancer development, such as CDH2, ZEB2, MAP3K2, and SLC24A4." (PMID 28298809, 2017). "Zinc finger E‐box binding protein 1 (ZEB1) and ZEB2 induce epithelial‐mesenchymal transition (EMT) and enhance cancer progression." (PMID 28618162, 2017). "A group of transcription factors have been demonstrated to be capable of orchestrating EMT program in cancer progression, such as Snail (SNAI1), Slug (SNAI2), ZEB2 (SIP1), ZEB1 and Twist1." (PMID 27121312, 2016). "Promotion of invasion and metastasis via interaction with transcription factors ZEB1 and ZEB2, involved in EMT in other cancer types." (PMID 27148353, 2016). "Gregory and colleagues reported evidence that suggests an essential role for the miR-200 family members in regulation of ZEB1 and ZEB2 genes and in the induction of epithelial to mesenchymal transition (EMT) in several types of cancer." (PMID 27039384, 2016). "Transcription factors, such as Snail, Slug, ZEB1, Twist, and ZEB2/SIP1, have been demonstrated to be capable of orchestrating EMT in cancer progression." (PMID 25645291, 2015). "The miR-200 family has also been shown to inhibit the EMT, stimulating the epithelial phenotype and cancer cell migration by direct targeting of the E-cadherin transcriptional repressors ZEB1 and ZEB2." (PMID 25970424, 2015). "Whole tissue sections from the same low-grade and high-grade budding cancers were immunostained for β-catenin, E-cadherin, CDX2, ZEB1 and ZEB2 and found to exhibit the expected protein phenotype." (PMID 25528769, 2015). "For example, the miR-200 family and miR-205 were shown to contribute to the EMT in cancer cells by directly targeting the transcriptional repressors of E-cad, ZEB1, and ZEB2." (PMID 26110567, 2015). "By inspecting the human exitron list, we found that EIS affects several cancer-related genes: the cancer marker genes BMI1, KRT5, and MUC1 and the genes involved in cell adhesion (CSF1), migration and metastasis (ZEB2 and KLF17)." (PMID 25934563, 2015). "ZEB2/SIP1 is a member of the deltaEF-1 family of two-handed zinc-finger factors and play vital roles in the development of a variety of cancers, such as gastric, ovarian, squamous and non-small cell lung carcinomas." (PMID 24626466, 2014). "As shown, these miRNAs are active regulators of the expression of several cancer-related mRNAs, including ZEB1, ZEB2, VIM, VEGFA, NTRK3 and SPDEF, and most of the miRNAs are cancer-related." (PMID 24512620, 2014).